CD163 (CD163 molecule)
Diseases named in the same sentence as CD163 in open-access papers (continued):
Sharing a sentence is not in itself a finding about the gene and the disease.
diabetes (continued). "Obese septic patients with diabetes were unique in displaying increased monocytic CD16 and CD163 expression." (PMID 36687421, 2022). "CD163 and CD206 were two markers for anti-inflammatory M2 microglia markers, and they were both increased in microglia from mice that had developed diabetes for 4 weeks." (PMID 35935990, 2022). "Muscle aging (Atrogin 1 and Glb1), diabetes (RAGE and CD163), and intracellular lipid accumulation (CD36 and PPARγ) related mRNA and protein expressions and FMOD were analyzed in MSTN knockout gas muscles." (PMID 34440852, 2021). "At 30 days, M2 macrophage markers Cd163, Mrc1 and Msr1 (CD204) were decreased in diabetes-prone animals." (PMID 31601915, 2019). "In addition, APX3330 promoted the polarization of M2 macrophages in the ischemic brain of type 1 diabetes mellitus (T1DM) stroke rats, as indicated by a decrease in ED1, an M1 macrophage marker, and increases in CD163, an M2 macrophage marker." (PMID 40746221, 2025). "Specifically, genes and cell surface markers involved in trans-endothelial migration and the recruitment of CD163+ monocytes were significantly suppressed and the expression of chemokine receptors CX3CR1, CXCL7 (PPBP), and CCR5 were down-regulated in those with diabetes complications." (PMID 39337580, 2024). "A significantly distinct functional profile of CD163+ monocytes was observed in this study between individuals who have diabetes with and without complications." (PMID 39337580, 2024). "The reduced presence of anti-inflammatory CD163+ monocytes in the systemic circulation would support the notion of a prolonged inflammatory state in the systemic environment of individuals with diabetes-related complications." (PMID 39337580, 2024). "In individuals with diabetes and cardiovascular disease, CD163+ cells were decreased in the atherosclerotic plaques compared to individuals with cardiovascular disease without diabetes." (PMID 39337580, 2024). "Using RNA-seq and mass cytometry, we observed that both RNA and phenotypic profiles of circulating CD163+ monocytes were different in those with diabetes and complications compared to those without complications." (PMID 39337580, 2024). "Although clinical studies found a correlation between the impaired scavenging of Hb-Hp complexes in diabetes mellitus, the effect of hyperglycemia on the expression and scavenging activity of CD163 in primary human macrophages has not been studied to date." (PMID 35163309, 2022). "Though in the past, literature has suggested the role of CD163 in periodontitis, however, its role in patients with diabetes mellitus and periodontal inflammation has not been explored so far." (PMID 32656036, 2020). "In this study, senescence markers (such as P16INK4a), inflammatory macrophage phenotypes (CD86, CD163, MCP-1), and immunometabolic enzymes (SDH, ACLY) were evaluated as downstream mechanistic responses to DN rather than as diagnostic criteria for diabetes or DN themselves." (PMID 41471323, 2025). "In addition, the function of antigen recognition by the CD163+ monocyte was decreased in individuals with diabetes and complications compared to those without, although a very low proportion of TLR4+ cells was detected in the CD163+ cells from both groups." (PMID 39337580, 2024). "Therefore, we aimed to comprehensively characterize circulating CD163+ monocytes, focusing on their functional profile and regulatory mechanisms, in individuals with long-duration diabetes, with or without complications." (PMID 39337580, 2024). "Additionally, the tissue presence of CD163+ macrophages in various diabetes complications was examined in a recent systematic review and was found to differ between individuals with and without diabetes complications." (PMID 39337580, 2024).
diabetes (continued). "The aim of the present study was to assess and quantify cluster of differentiation 163 (CD163) protein levels and CD163 messenger RNA (mRNA) gene expression in subgingival plaque samples of generalized chronic periodontitis subjects with and without type II diabetes mellitus (DM)." (PMID 32656036, 2020).
liver disease (48 papers, 2013 to 2025). "Systemic inflammatory markers such as C-reactive protein (CRP), lipopolysaccharide (LPS), interleukin-6 (IL-6), tumor necrosis factor-alpha (TNF-α), soluble CD14 (sCD14), soluble CD163 (sCD163), and D-dimer are linked to cardiovascular and liver diseases." (PMID 39529759, 2024). "Soluble CD163 is associated with fibrosis in patients with HCV and HBV, and sCD163 levels are elevated in patients with acute-on-chronic hepatitis B liver failure and positively associated with end-stage liver disease." (PMID 37626844, 2023). "CD163 has been independently associated with incidence of chronic kidney, lung, and liver disease in treated individuals with HIV." (PMID 34211989, 2021). "Soluble CD163 (sCD163) has been identified as a specific macrophage activation marker associated with the severity of liver disease and provides a potential target for therapeutics." (PMID 33117329, 2020). "Macrophages play a significant role in chronic liver disease as reflected by elevated soluble (s)CD163 and mannose receptor (sMR) levels and associated with liver disease severity and prognosis." (PMID 30183743, 2018). "M1-like macrophage infiltration was inhibited upon various liver diseases, and the proportion of CD163+ and DP M2-like macrophages was increased in HBsAg_low/HBV_HCC/NAFL." (PMID 38032223, 2024). "The soluble forms of CD163 (sCD163) and MR (sMR), that are present in plasma and body fluids, have been thoroughly investigated as macrophage-related biomarkers in liver diseases." (PMID 33868313, 2021). "Two of the best studies on macrophage-associated prognostic markers include soluble CD163 (sCD163)+ and CD204+ TAMs, with particular utility in the context of liver disease and various cancers, respectively." (PMID 33763066, 2021). "As recently reviewed macrophage activation markers soluble (s)CD163 and soluble mannose receptor, sMR, are associated with chronic liver disease severity (Child-Pugh and MELD scores) and portal hypertension." (PMID 34177608, 2021). "Soluble CD163 (sCD163) is upregulated during macrophage proliferation and activation and is a marker for diagnosis of the severity and progression of liver disease." (PMID 33763066, 2021). "Here, we review the existing literature on soluble CD163 and soluble mannose receptor in liver diseases with a particular focus on their relationship to hepatic fibrosis in metabolic associated fatty liver disease, as well as in chronic hepatitis B and C." (PMID 33490096, 2020). "The macrophage activation markers soluble (s)CD163 and soluble mannose receptor (sMR), are associated with portal hypertension in patient with liver cirrhosis but never investigated in patients with non-cirrhotic portal hypertension." (PMID 34177608, 2021). "Moreover, CD163, which is a marker for monocyte/macrophage lineage, is highly expressed in various inflammatory disorders including hepatic diseases." (PMID 32357508, 2020). "Both CD163 and CD206 have recently been detected in blood samples, and the levels have been found to be closely associated with several disease states including infections and some liver diseases." (PMID 32909942, 2020). "Interestingly CA9 levels correlated with markers of portal hypertension (soluble CD163 and platelet count) and is significantly increased in patients with diagnosed esophageal varices supporting further investigations in cirrhotic patients and as a marker for portal hypertension." (PMID 30011326, 2018). "To investigate the relative contribution of macrophages in liver diseases, we applied SPADE to CD45, CD11b, F4/80, CD163, CD80, and PD-L1 to compartmentalize macrophages." (PMID 38032223, 2024). "We intend to review the literature on macrophage activation as part of the immune response in liver diseases, especially in ACLF, with a focus on the soluble forms of CD163 and CD206 as biomarkers for ACLF disease severity and prognosis." (PMID 32397365, 2020).
liver disease (continued). "Soluble CD163 (sCD163) is shed in the blood circulation by activated macrophages and correlates strongly with the hepatic venous pressure gradient (HVPG) and is thereby a good indicator of portal hypertension." (PMID 30011326, 2018).
lung carcinoma (44 papers, 2015 to 2025). "Studies have shown that the high level of positive macrophages in terms of CD163 in BALF is associated with poor survival in patients with lung cancer." (PMID 37958349, 2023). "The phenotype of tumor-associated macrophages in lung cancer is characterized by M2 class markers, such as CD163, CD204, and MARCO, which are transmembrane receptors." (PMID 35369515, 2022). "Taken together, significant accumulation of CD163+ TAMs in MPE caused by lung cancer is closely correlated with poor prognosis." (PMID 25871392, 2015). "We examined whether the infiltrating M2 tumor associated macrophages (M2 TAM, CD163+) were enriched in the area of Rab37+CHI3L1+ cells in tumor specimens from lung cancer patients." (PMID 34987649, 2022). "We further found that the expression of TSG6, CD44, CD68, and CD163 (marker of TAMs) is elevated in metastatic lung cancer tissues of mice driven by active PLK1." (PMID 40860188, 2025). "In CRC and lung cancer we also observed high expression of APOE, encoding Apolipoprotein E, restricted to CD68+CD163+ macrophages." (PMID 36724681, 2023). "The expression of integrin subunit alpha M, CD27, and CCL5 is upregulated in lung cancer tissues with CD163+ cell infiltration." (PMID 37744276, 2023). "Chen L. et.al have shown that infiltrating CD163-positive macrophages are the predominant population in BALF from lung cancer patients." (PMID 37958349, 2023). "To determine the macrophage phenotype, we used the IHC to detect the expression of M2 marker protein CD163 in lung cancer tissue and adjacent tissue." (PMID 35897096, 2022). "In that study, infiltration of macrophages and CD56dim-NK-cells was increased in lung cancer BM, similar to the increased CD163-positive M2 to iNOS-positive M1 macrophage and NCR1-positive NK cell to CD3-positive T-cell ratios." (PMID 34638378, 2021). "Overall, these results indicate the crucial role of CD163 + TAMs at invasive front which promote tumor expansion and affect lung cancer patients survival." (PMID 34326381, 2021). "Taken together, this study demonstrates the key role of circRNAs circPTK2/circHIPK3 in Kras-related lung cancer progression through infiltration of CD163+/CD206+ M2 macrophages and monocytic MDSC subset (Gr1−/CD11b−, Gr1−/CD11b+) recruitment." (PMID 34326381, 2021). "Using immunostaining, we observed that CD163+ TAMs closely surrounded Spi-B-positive tumor cells in human lung cancer tissues." (PMID 34141615, 2021). "In human lung cancer tissues, TAMs expressing CD163 surrounded and infiltrated the cancer mass of strong Spi-B staining." (PMID 34141615, 2021). "When immunostained tissue sections were quantified, a highly significant positive correlation was found between Spi-B+ cells in lung cancers and CD163+ macrophages." (PMID 34141615, 2021). "In lung cancer patients of Italian cohort, CD163+CD33+PD-L1+ macrophages with epithelioid morphology (alveolar macrophage-like) defined by the authors as “complete immunophenotype,” were detected in all patients with hyperprogression." (PMID 33194645, 2020). "CD163+ macrophages were the predominant macrophage subpopulation detected in bronchoalveolar lavage fluid (BALF) from lung cancer patients." (PMID 33194645, 2020). "TAM phenotype in lung cancer is characterized mostly by M2-like markers, such as CD163, CD204, and MARCO." (PMID 33194645, 2020). "The significant accumulation of CD163+ TAMs in malignant pleural effusion of lung cancer patients closely correlated with reduced PFS." (PMID 33194645, 2020). "IHC analysis of 213 cases of human lung adenocarcinoma specimens revealed that PD-1 is preferentially expressed by CD163+ TAMs in the tumor stroma, and these stromal PD-1+ TAMs were an independent predictor of reduced survival in lung cancer patients." (PMID 33194645, 2020). "Our results demonstrated that the percentages of CD206+/CD163+ cells were significantly higher in SSc-ILD than in lung cancer or sarcoidosis and/or GM-MDMs." (PMID 29562615, 2018).
lung carcinoma (continued). "Kaplan-Meier analysis of overall survival in lung cancer patients based on IL-34 and CD163 expression showed that patients with high expression of both IL-34 and CD163 have the poorest survival compared to other groups." (PMID 29323162, 2018). "Immunohistochemical staining of IL-34, M-CSF, CSF1R and CD163 was performed on lung cancer tissues obtained from patients by surgical resection." (PMID 29323162, 2018). "Next, we examined the relation between M-CSF or IL-34 with CD163 expression and its impact on survival in this cohort of lung cancer patients." (PMID 29323162, 2018). "We quantified FN expression in mouse lung tissues and human lung cancer tissues as densities of overlay density of FN(green) and CD11b(Violet) in mouse lung or overlay density of FN(green) and CD163(blue) in human lung cancer tissue." (PMID 30272511, 2018). "By double IHC, the detection of 20.1% of CD68+CD163- AMs among CD68+CD163+ AMs in lung tissue adjacent to the cancer margin suggested that AMs in lung tissue adjacent to lung cancer were mostly composed of M2 macrophages." (PMID 26900851, 2016). "The results showed that CD163+ TAMs in lung cancer patients with MPE is an independent prognostic factor for PFS." (PMID 25871392, 2015). "Moreover, the accumulation of CD163+ macrophages is closely correlated with a poor prognosis in lung cancer, and the increased density of CD68+CD163+ macrophages in tumor nests and stroma was associated with lymph node metastases." (PMID 36077342, 2022). "CD163 signal in tumor tissue from lung cancer patients was detected by immunohistochemical (IHC)." (PMID 35897096, 2022). "Firstly, we found a strong CD163 signal in tumor tissue from lung cancer patients by IHC." (PMID 35897096, 2022). "In the CD68+ CD163+ M2 macrophage population, FRβ expression in lung cancer tissues was ~84–96%." (PMID 32296026, 2020). "Immunohistochemical staining showed that CD163 expression could be detected in lung cancer tissues with a variety among patients." (PMID 29323162, 2018). "In lung cancer, correlation of TAMs with outcome depends on TAMs subsets and intratumoral distribution, as M2 type (CD163+) and stromal TAMs are correlated with poor outcome, while M1 type (HLA-DR+) and intraepithelial TAMs are correlated with favorable outcome." (PMID 28038471, 2017). "The prognostic value of CD163+ macrophages in MPE was evaluated in lung cancer." (PMID 25871392, 2015). "Therefore, CD163+ TAMs in lung cancer patients with MPE was an independent prognostic factor for PFS." (PMID 25871392, 2015). "They observed elevated levels of inflammatory factors and more CD163-positive macrophages in lung cancer compared with benign ones, which reflects the local environmental status of host immunity and may be helpful in the diagnosis of lung cancer." (PMID 37958349, 2023). "CCR7 and CD163 could be used as markers of macrophage polarization in lung cancer microenvironment." (PMID 34367284, 2021). "To determine whether Spi-B expression promotes TAM infiltration in human lung cancer tissues, we examined the expression of CD163 and Spi-B in tissue samples obtained from 79 NSCLC patients admitted to the Tianjin Medical University Cancer Institute and Hospital." (PMID 34141615, 2021). "Here we observe a rise in MALAT1 expression, correlating with increased levels of MCP-1 and CD68, CD163, CD206, indicative of M2 macrophages in tumor tissues of AA lung cancer patents." (PMID 38791954, 2024). "Forced MALAT1 expression led to enhanced growth and invasiveness of lung cancer cells, both in vitro and in vivo, accompanied by elevated levels of MCP-1, CD68, CD163, CD206, and KI67." (PMID 38791954, 2024). "CD163 expression in BALF alveolar macrophages is higher in the IPF patients compared to both healthy controls and lung cancer patients." (PMID 39184076, 2024).
lung carcinoma (continued). "Our results from the NSCLC discovery cohort were validated by single-cell sequencing of three lung carcinomas where LAIR-1 was highly expressed on CK8/CK10+ tumor cells and CD68+ and CD163+ macrophages." (PMID 36960400, 2023). "In line with our mouse data, CB1 and CB2 expression were not only seen in lung cancer cells, but also in infiltrated immune cells, such as CD3+ T and CD8+ T cells, NKp46/NCR1+or CD56+ NK cells, and CD163+ macrophages." (PMID 36700219, 2022). "As M2-like tumor associated macrophages (TAMs) are commonly found in the TME of lung carcinoma, M2 markers CD206 and CD163 were evaluated." (PMID 33968758, 2021). "In our study, AM of patients suffering from SSc-ILD, in comparison with AM from lung cancers, also had a significantly enhanced expression of the M2 polarization marker CD206 and a higher percentage of positive cells for CD169 and CD163." (PMID 29562615, 2018). "As expected, 60% of cancer tissues that showed high expression of IL-34 were accompanied with high expression of CD163, and the absence of CD163 staining was frequently associated with negative staining of IL-34, which indeed suggests a correlation between IL-34 and CD163 expression in lung cancers." (PMID 29323162, 2018). "Immunohistochemistry revealed that CD163 and SOX9 expression were positively correlated in specimens from 164 lung cancer patients." (PMID 29245941, 2017). "To determine if SOX9 expression is correlated with number of TAMs, we analyzed the distribution of TAMs (CD163+ macrophages) and SOX9 in specimens from lung cancer patients using immunofluorescent staining." (PMID 29245941, 2017). "The neoplastic cells were positive for CD68 and CD163 and negative for epithelial antibodies; therefore, lung cancer was excluded." (PMID 36915094, 2023). "Notably, CD163 + CD14+ DCs were found to be abundant in early- and advanced-stage lung cancer primary tissues but less abundant in metastatic lymph nodes and LUAD-BM." (PMID 37760494, 2023). "However, the expression levels of CD163, CD169, CD204, CD64 and CD36 were significantly higher in SSc-ILD than in lung cancers." (PMID 29562615, 2018). "In many entities and especially in lung cancer, TAMs seem to polarize to a so called M2 state, which is characterized by CD204 and CD163 expression and promotes tumorigenesis, angiogenesis, remodeling of the extracellular matrix and suppression of immune response." (PMID 30018308, 2018). "Based on an analysis of the ONCOMINE database, high MCT-1 levels were positively correlated to CD31 (Pearson correlation +0.62, P=0.01), α-SMA (Pearson correlation +0.15, P=0.03) and CD163 (Pearson correlation +0.35, P<0.001) expression in stage III/IV and different types of lung cancers." (PMID 28394354, 2017). "As for the micro-distribution of TAMs and survival, low density of CD68+ TAMs and CD68+HLA-DR+ M1 TAMs in lung cancer islet were both associated with poor OS, while islet CD68+CD163+ M2 TAM density was not correlated with prognosis." (PMID 27144518, 2016). "As CD163 can also be detected in lung cancer cells by immunohistochemistry, analysis of CD163 might not be adequate to evaluate TAMs in lung cancers." (PMID 37190178, 2023). "Moreover, it was demonstrated that monocyte-derived macrophages co-expressing CD206, CD163 and CD169 were significantly higher in SSc-ILD than in lung cancer or sarcoidosis and that a similar macrophage phenotype was obtained from the analysis of blood-monocytes derived macrophages in SSc patients." (PMID 30249259, 2018). "In addition, immunohistochemistry analysis using anti-human CD163 antibody was performed on the lung sections of two patients with DM-related ILD (a survivor and non-survivor, respectively) and one patient with early-stage lung cancer as a normal control." (PMID 28103926, 2017).